ENSG00000239920 (novel transcript)
Gene: Protein-coding gene on chromosome 11 (5,254,392 to 5,678,434, reverse strand). Ensembl gene ENSG00000239920.
Genetic constraint (gnomAD): Missense variants: 91 observed, 90.9 expected, observed/expected ratio (o/e) 1, 90% interval 0.84 to 1.19. Synonymous variants: 43 observed, 37.04 expected, observed/expected ratio (o/e) 1.16, 90% interval 0.91 to 1.5.